GAST (gastrin)
Description:
Gastrin stimulates the stomach mucosa to produce and secrete hydrochloric acid and the pancreas to secrete its digestive enzymes. It also stimulates smooth muscle contraction and increases blood circulation and water secretion in the stomach and intestine.
Synonyms: GAS
Tractability: Small molecule: a structure with a bound ligand is known. Antibody: its Gene Ontology location is reachable by antibodies, with high confidence; UniProt places it where antibodies can reach, with medium confidence; UniProt predicts a signal peptide or a membrane-spanning region.
Gene: Protein-coding gene on chromosome 17 (41,712,331 to 41,715,969, forward strand). Ensembl gene ENSG00000184502.
Subcellular location: Secreted
Pathways (Reactome):
Signal Transduction: G alpha (q) signalling events; Gastrin-CREB signalling pathway via PKC and MAPK
Gene Ontology:
Molecular function: protein binding; hormone activity
Biological process: G protein-coupled receptor signaling pathway; response to food; signal transduction
Cellular component: extracellular region
Genetic constraint (gnomAD): Loss-of-function variants: 9 observed, 12.18 expected, observed/expected ratio (o/e) 0.74, 90% interval 0.44 to 1.29. The upper end of that interval is the gene's LOEUF score, 1.29, which puts it in group 5 of 6, group 1 being the genes least tolerant of losing a copy. Missense variants: 117 observed, 126.07 expected, observed/expected ratio (o/e) 0.93, 90% interval 0.8 to 1.08. Synonymous variants: 50 observed, 51.04 expected, observed/expected ratio (o/e) 0.98, 90% interval 0.78 to 1.24.
Homologues: Orthologues: chimpanzee GAST (100% identical), macaque GAST (93% identical), dog GAST (79% identical), pig GAST (74% identical), rat Gast (70% identical), mouse Gast (69% identical), rabbit GAST (69% identical), guinea pig GAST (54% identical), tropical clawed frog gast (31% identical), tropical clawed frog xt6l (26% identical).
Diseases named in the same sentence as GAST in open-access papers:
GAST is named in the same sentence as 231 diseases in open-access papers, as found by Europe PMC text mining. Sharing a sentence is not in itself a finding about the gene and the disease. The quoted sentences say what the papers report.
gastric cancer (130 papers, 1991 to 2026). A primary or metastatic malignant neoplasm involving the stomach. "This protective effect of gastrin contrasts with clinical observations where hypergastrinemia is associated with increased gastric cancer risk, highlighting species-specific differences in gastrin signaling." (PMID 40673273, 2025). "When these confounding factors are excluded, elevated gastrin levels can serve as an indirect marker of extensive mucosal atrophy, which is itself a significant risk factor for gastric cancer development." (PMID 40995608, 2025). "Hypochlorhydria or achlorhydria, regardless of the cause, leads to a compensatory increase in serum gastrin, a potent inducer of gastric epithelial cell proliferation and a risk factor for gastric cancer." (PMID 40722622, 2025). "Long term use of PPIs is also associated with an increased risk of gastric cancer, with one possible explanation attributed to elevated levels of gastrin and alterations in the microbiome." (PMID 39840081, 2024). "The prolonged hyperstimulation by HIF causing CCRCC resembles how excessive gastrin hyperstimulation leads to gastric cancer and is another example of cancer developing from a differentiated cell exposed to prolonged hyperstimulation." (PMID 38660133, 2024). "Previous studies have reported that gastrin levels correlate more closely with intestinal metaplasia than with atrophic gastritis, and intestinal metaplasia is a known risk factor for gastric cancer." (PMID 39518740, 2024). "Background and Objective: Serum markers such as gastrin and pepsinogen are useful for stratifying gastric cancer risk." (PMID 39518740, 2024). "The H. pylori infection causes an imbalance between somatostatin and gastrin, which promotes chronic inflammation and the development of gastric cancer." (PMID 39234535, 2024). "The classification used for the DSC test to predict gastric cancer risk combines the coefficient of the patient’s age and sex and serum pepsinogen I and II, gastrin 17, and anti-Helicobacter pylori immunoglobulin G concentrations in two equations: Y1 and Y2." (PMID 36834698, 2023). "This study aimed to evaluate pepsinogens (PGIs) and gastrin-17 (G-17) levels and to determine the diagnostic performances for gastric cancer and chronic atrophic gastritis among Mongolian individuals." (PMID 36251649, 2022). "They highlighted that PPIs reduce gastric acid production, and consequently accelerate the secretion of gastrin, which is linked to an increase in the risk of gastric cancer." (PMID 35804824, 2022). "In earlier research using murine models, high and low expression of gastrin were closely associated with an increased risk of gastric cancer." (PMID 34976177, 2022). "We have previously reported that the PGI/PGII ratio and serum gastrin level are associated with the Helicobacter pylori (H. pylori) infection status and that the risk of gastric cancer can be determined by measuring the PGI level and the PGI/II ratio." (PMID 35126509, 2022). "Some national guidelines, such as those from Brazil, also support the use of serology (PgI, PgII, H. pylori and gastrin-17) to identify populations at risk of developing gastric cancer." (PMID 35885649, 2022). "Gastrin has long been suspected to be a potential risk factor of gastric cancer by ensuring hypergastrinemia." (PMID 35804824, 2022). "Third, we targeted ESD patients as study subjects since we intended to assess how gastrin and PG levels changed in those who were at high risk of developing gastric cancer." (PMID 35126509, 2022). "Our study is aimed at revealing the mechanism underlying the effect of gastrin on apoptosis of gastric cancer cells." (PMID 33937399, 2021). "Given that gastrin is in close association with gastric cancer, CCK2R, the identified receptor for gastrin, became one of the major research interests." (PMID 34831211, 2021).
gastric cancer (continued). "Individuals with elevated gastrin have been shown to have an increased risk of developing gastric cancer, and some studies have reported increased gastrin in patients with gastric cancer." (PMID 34202596, 2021). "Our findings can provide experimental evidence and lay the foundation for further understanding the mechanism underlying the antiapoptosis effect of gastrin in gastric cancer cells." (PMID 33937399, 2021). "In conclusion of this part, H. pylori, autoimmune gastritis and PPIs all predispose to gastric cancer via gastrin." (PMID 34207192, 2021). "Some other researches similarly found high level of serum gastrin was associated with precancerous lesions and gastric cancer in Asians44–47." (PMID 32161305, 2020). "It is probable that Helicobacter pylori infection (the most important cause of gastric cancer), as well as drugs inhibiting gastric acid secretion induce gastric cancer in the long-term, due to an elevation of gastrin caused by reduced gastric acidity." (PMID 33266504, 2020). "Gastrin is associated with the development and progression of gastrointestinal malignancies, including gastric cancer and colorectal cancer." (PMID 32784492, 2020). "They carried expectations of a fundamental shift in capacity—a potential game-changer with regard to understanding the causal mechanisms underlying stomach cancer and the role of gastrin therein." (PMID 32468194, 2020). "In antrum gastritis, Hp provokes an increase in gastrin secretion which leads to greater production of gastric acid, which renders subjects more susceptible to peptic ulcers, but less predisposed to gastric cancer (GC)." (PMID 31216758, 2019). "Since Hp predisposes to gastric cancer only when having induced oxyntic atrophy, we have proposed that the carcinogenic effect of Hp infection is mediated by gastrin." (PMID 31108898, 2019). "There are also arguments for a role of gastrin in the pathogenesis of gastric carcinomas, as patients with autoimmune gastritis have increased risk of malignancy." (PMID 31108898, 2019). "In the case of the stomach, there is evidence of increased expression in gastric cancer that is associated with poor outcome; moreover, there are direct effects of gastrin, and of H. pylori, in inducing PAI-1 in epithelial cells." (PMID 23494120, 2013). "MMP-7 is also identified as a target of gastrin in hypergastrinemia that is associated with gastric cancer." (PMID 20939893, 2010). "Thus, an increased level of gastrin was associated with gastric cancer risk, although it cannot predict gastric cancer stage." (PMID 38255710, 2024). "Thus, inflammation and gastrin are successive pathogenetic factors in gastric cancer caused by H. pylori." (PMID 37941554, 2023). "Since we do not know the etiology or pathogenesis of autoimmune gastritis nor have any treatment influencing its progression, the only way of reducing the gastric cancer risk in patients with autoimmune gastritis is endoscopic control until a gastrin antagonist becomes clinically available." (PMID 37941554, 2023). "It will cause the changes of pepsinogen and gastrin, thus increasing the risk of gastric cancer." (PMID 35918654, 2022). "Interestingly, gastrin-17 was negatively associated with the relative abundance of Bifidobacterium and Lactobacillus in the intestines of patients with gastric cancer." (PMID 35454944, 2022). "In addition, a role of H. pylori, pepsinogen I and, to a less degree, gastrin as the risk factors in gastric cancer has been confirmed." (PMID 35163805, 2022). "Moreover, knockdown of gastrin is associated with deactivation of NF-κB in a ROS-dependent manner in gastric cancer cells and upregulation of Bax and downregulation of Bcl-2, thus promoting apoptosis." (PMID 33937399, 2021). "Gastrin is associated with gastric cancer proliferation by an autocrine mechanism." (PMID 32784492, 2020).
gastric cancer (continued). "Elevation of gastrin may be the carcinogenic factor for Helicobacter pylori as well as the recently described increased risk of gastric cancer due to proton pump inhibitor treatment." (PMID 30567376, 2018). "Gastrin therefore may be the common pathogenic factor for gastric carcinomas originating from the oxyntic mucosa, where there are cells that are stimulated by gastrin receptor agonist." (PMID 30567376, 2018). "According to a previous study, gastrin and cholecystokinin were associated with NETs; this resulted in tissue growth in the gastrointestinal tract and carcinogenesis that led to colorectal and gastric cancers." (PMID 25427657, 2014). "Thus, it was not entirely surprising when several laboratories reported that gastrin knockout (GAS-KO or GAS−/−) mice were also susceptible to stomach cancer." (PMID 24216700, 2013). "High-risk events of gastric cancer included a history of gastric ulcer, Helicobacter pylori infection, serological atrophic gastritis (serum pepsinogens), hypergastrinemia (serum gastrin-17), and endoscopic findings of atrophic gastritis, gastric polyps, and gastric ulcer." (PMID 41899344, 2026). "Insulin-gastrin-secreting (INS-GAS) mice are genetically susceptible to GC and are therefore commonly used in developing mouse gastric cancer models." (PMID 37583514, 2023). "Moreover, our results also showed that gastrin knockdown caused reduction of Bcl-2 levels and elevation of Bax levels in a ROS-dependent manner, indicating that gastrin knockdown promotes gastric cancer cell apoptosis by modulating the expression levels of Bax and Bcl-2." (PMID 33937399, 2021). "Thus, we examined whether knockdown of gastrin is associated with deactivation of NF-κB in a ROS-dependent manner in gastric cancer cells." (PMID 33937399, 2021). "Moreover, the central role of gastrin is demonstrated by the fact that the most important cause of gastric cancer, Helicobacter pylori infection, predisposes to gastric cancer only after having induced oxyntic atrophy, which necessarily leads to hypergastrinemia." (PMID 32796591, 2020). "Humanized insulin/Gastrin (INS-GAS) transgenic mice are frequently used to model stomach cancer as they have high circulating levels of pancreatic gastrin." (PMID 40438238, 2025). "In our study, patients with gastric cancer exhibited higher mean serum gastrin levels compared with those with other gastric conditions." (PMID 40995608, 2025). "Male and female transgenic FVB/N insulin-gastrin (INS-GAS) mice as a model of gastric cancer were randomly administered Brucella Broth or Helicobacter pylori (H. pylori)." (PMID 39985099, 2025). "Further studies using N-nitroso compounds (MNU) to induce gastric cancer in various genetic backgrounds revealed that GAS−/− mice exhibited greater susceptibility to gastric cancer following MNU treatment, while gastrin overexpression conferred resistance." (PMID 40673273, 2025). "In this study, we demonstrate that transgenic FVB/N insulin-gastrin (INS-GAS) mice that develop gastric carcinoma with H. pylori infection were protected from cancer development with Smox deletion." (PMID 39523394, 2025). "Gastrin 17 is produced in the antral part of the stomach and has recently been proposed as a predictor for both gastric atrophy and gastric cancer." (PMID 38255710, 2024). "This would be parallel to gastric cancers, where gastrin stimulates the proliferation of ECL cells leading to ECL cell NETs and gastric carcinoma of diffuse type." (PMID 38660133, 2024). "Gastrin acts as a regulator of gastric cancer growth and activates the ERK-P65-miR23a/27a/24 pathway." (PMID 38392199, 2024). "As previously discussed, serum gastrin is considered a marker of both gastritis and gastric cancer, and it is well-known that the oral administration of PPIs can increase gastrin levels." (PMID 39518740, 2024). "The serum gastrin level is included as one of the indices in the GastroPanel for predicting the development of gastric cancer." (PMID 39518740, 2024).
gastric cancer (continued). "The imbalance between somatostatin and gastrin further leads to chronic inflammation and the occurrence of gastric cancer." (PMID 39234535, 2024). "Gastrin, Pepsinogen I (PG I), Pepsinogen II (PG II), and the PG I/II ratio were used to predict metachronous gastric cancer after the eradication (GCAE) of lesions." (PMID 39518740, 2024). "Gastrin has also been shown to stimulate the growth of human gastric cancer cell lines in cell culture." (PMID 39518740, 2024). "Gastrin expression is upregulated in many gastric carcinomas of the stomach corpus, including endocrine tumors." (PMID 39720008, 2024). "Serum PG I, PG II, PG I/II ratio, and gastrin have been reported as potential serological biomarkers to screen for atrophic gastritis in Iran, a country with a high incidence of gastric cancer." (PMID 37210509, 2023). "Gastrin, an inducer of gastric acid secretion, has been shown to be a valuable screening marker for gastric cancer." (PMID 37359529, 2023). "Hypergastrinemia due to atrophic oxyntic gastritis also predisposes affected individuals to gastric cancer of the intestinal type, presumably originating from stem cells stimulated directly or indirectly (Reg protein from ECL cells) by gastrin." (PMID 37941554, 2023). "The central role of gastrin in gastric carcinogenesis provides an opportunity to prevent many gastric cancers." (PMID 37941554, 2023). "It is probable that gastrin is the pathogenetic factor for gastric cancer due to H. pylori, autoimmune gastritis, and long-term prolonged inhibition of gastric acid secretion." (PMID 37941554, 2023). "In particular, we will focus on the role of neuroendocrine cells, mainly the enterochromaffin-like (ECL) cells, in gastric cancer, and the role of gastrin in the pathogenesis of gastric cancers, especially those due to H. pylori." (PMID 37941554, 2023). "Our previous study observed that the CCK-BR and gastrin mRNA and protein were co-expressed in human gastric cancer cell lines and gastric cancer tissues, and downregulation of CCK-BR affected cell proliferation and apoptosis in gastric cancer cells." (PMID 34976177, 2022). "We aimed to evaluate the clinical applicability of a new scoring system that comprises the variables age, sex, pepsinogen ratio (PGR), gastrin-17 (G-17), and Helicobacter pylori (Hp) infection for gastric cancer (GC) screening in the Wannan region, China." (PMID 35739473, 2022). "In this study, we further investigated the effects of gastrin/CCK-BR autocrine/paracrine signaling on cell invasion and metastasis and underlying mechanisms in gastric cancer." (PMID 34976177, 2022). "In conclusion, the present findings revealed a gastrin/CCK-BR autocrine/paracrine signaling loop in gastric cancer cells, which plays a significant role in the invasion and metastasis of cancer cells by promoting MMP-2 and VEGF expression." (PMID 34976177, 2022). "In this study, we established six gastric cancer cell lines with enhancement or inhibition of gastrin/CCK-BR signaling by overexpression or knockdown of gastrin in cells to confirm that a functional gastrin/CCK-BR loop existed in gastric cancer cells." (PMID 34976177, 2022). "After the stable cells overexpressing gastrin were exposed to proglumide (5 mmol/L) for 48 h, both cell growth rate and colony formation rate were significantly decreased, suggesting that the gastrin/CCK-BR loop is involved in gastric cancer cell growth." (PMID 34976177, 2022). "In pathological conditions like gastric cancer, gastrin exerts growth-promoting effects in the oxyntic mucosa and gastric epithelial cells." (PMID 34976177, 2022). "Gastrin also can stimulate cholecystokinin β receptors (CCKβR), leading to the growth of gastric cancer tumor cells." (PMID 35650297, 2022).